CRP (C-reactive protein)
Diseases named in the same sentence as CRP in open-access papers (continued):
Sharing a sentence is not in itself a finding about the gene and the disease.
Sepsis (continued). "WBC, CRP, and PCT have been widely used as biomarkers in nearly all studies of infection, but these biomarkers still have false positives and negatives in the diagnosis of infection and sepsis." (PMID 32508526, 2020). "In contrast, WBC and CRP alone or combined together do not show any advantage on the diagnosis of sepsis, whose AUCs are between 0.5 and 0.6." (PMID 32508526, 2020). "Currently, there are many nonspecific markers for diagnosing sepsis, which include: white blood cell count, C-reactive protein (CRP), TNF-alpha, and interleukins." (PMID 32467788, 2020). "Previous studies demonstrated CRP lack specificity for sepsis due to an increase in non-infectious inflammatory conditions." (PMID 33292630, 2020). "We first monitored the plasma proteome profiles from these patients across the different time points to elucidate changes in protein abundances associated with sepsis, confirming that several proteins, including CRP, AACT, and several other APPs, became higher abundant at the onset of sepsis." (PMID 33519818, 2020). "In that same study, CRP levels were not decreased, which was probably due to the late administration of Vit C in advanced stages of sepsis before developing acute respiratory distress syndrome (ARDS)." (PMID 33213070, 2020). "In addition, miR-10a levels in PBMC were also significantly correlated to levels of CRP (r = −0.418, p = 0.007) and PCT (r = −0.323, p = 0.039), two popular biomarkers of sepsis." (PMID 32214905, 2020). "We did, for example, not collect data on comorbidities systematically nor lactate or c-reactive protein levels in the non-sepsis cohort." (PMID 33148300, 2020). "Regarding the improved sepsis group, significantly different values between both initial and follow-up evaluations were documented by each of the following sepsis parameters: nCD64%, P-SEP, hs-CRP, PLT, nCD64 MFI, ANC, and Hb." (PMID 33204274, 2020). "In our opinion, although PCT was the best diagnostic marker, due to being expensive, we advise restricting using it in neonatal sepsis cases with clinical symptoms of sepsis with negative CRP to prove sepsis." (PMID 33061986, 2020). "In sepsis patients, SIRT1 negatively correlated with serum creatinine (Scr), white blood cells (WBC), C-reactive protein (CRP), acute physiology, and chronic health evaluation II (APACHE II) score, and sequential organ failure assessment (SOFA) score, while it positively correlated with albumin." (PMID 33263643, 2020). "The matching process resulted not only in good balance between groups regarding matched covariates (age, gender, bilirubin, creatinine, thrombocytes, leukocytes, c-reactive protein (CRP), procalcitonin (PCT), lactate), but also regarding suspected pathogen, sepsis source, and comorbidities." (PMID 33255912, 2020). "CRP had significantly higher values for patients with septic shock compared to those with sepsis or for non-survivors compared to survivors." (PMID 33374939, 2020). "Although these doses are lower than those typically administered in Western countries, the administration of dexmedetomidine at these lower doses successfully decreased CRP and PCT levels and increased albumin levels when administered to patients with sepsis for 14 days." (PMID 32778146, 2020). "The current study proved that CRP is an effective biomarker for the differentiation between patients with sepsis and those without (P < 0.001) which is confirmed by some studies while rejected by others." (PMID 32832553, 2020). "CRP and PCT played a prominent role in diagnosing AC patients with sepsis from the healthy control." (PMID 32508526, 2020). "It has been shown that no combination of biomarkers performs well in diagnosing sepsis like CRP alone." (PMID 32238170, 2020).
Sepsis (continued). "The goal of this study was to assess the efficacy of presepsin as a severity and mortality prognosis marker for sepsis patients compared to other inflammation or infection indicators, such as leucocytes, erythrocyte sedimentation rate (ESR), or C reactive protein (CRP)." (PMID 33374939, 2020). "Currently, the gold standard for sepsis diagnosis is blood microbiological culture analysis, but this method spends more time to get the examination results than other molecular biomarkers, such as procalcitonin (PCT) and C-reactive protein (CRP)." (PMID 32455124, 2020). "This is the first study to use a nomogram to develop a novel prediction model that shows that WBC, anemia, PCT, CRP, albumin, and ALT may help clinicians differentiate KD from sepsis with high accuracy." (PMID 32792679, 2020). "Significant increase in nCD64 (P < 0.001) and hs-CRP (P=0.018) values was observed in severe sepsis/septic shock patients compared to nonsevere sepsis patients." (PMID 33204274, 2020). "Herein, CRP and IL-6 levels were significantly higher in patients with sepsis than in those without sepsis at hospital admission." (PMID 33178716, 2020). "A positive correlation between suPAR and CRP was also reported for critically ill intensive care patients with or without sepsis and prosthetic joint infection." (PMID 31727136, 2019). "Combination of normal immature to total neutrophil Ratio with negative CRP values in neonates with presumed sepsis is an indicator of non-infected neonate which comprised 78.8% of our study population." (PMID 30881431, 2019). "C-reactive protein (CRP) is a powerful biomarker for inflammation, infection and sepsis." (PMID 31262326, 2019). "Similar differences between patients with sepsis compared to patients without sepsis were found for CRP level, PCT level and lymphocyte counts." (PMID 30811475, 2019). "Moreover sCD14-ST seems to be fast and more rapid-responding then CRP (increases after 12–24 h) and also PCT (increases after 3–4 h) with plasma levels already increased at sepsis onset (t = 0)." (PMID 31159729, 2019). "For example, NT-proBNP may be influenced by myocardial dysfunction in patients with severe sepsis and septic shock; PCT and CRP have also been evaluated as predictors for patients with surgery." (PMID 30733876, 2019). "Standardisation of the assessment process may be aided by the inclusion of objective variables to capture evidence of infection or sepsis, along with markers of severity including qSOFA score, NEWS, C-reactive protein (CRP), and white blood cell count." (PMID 31035663, 2019). "The results of this study suggest that IL-6 is better than PCT and CRP in predicting the treatment success in predominantly non-surgical sepsis in the first 48–72 h." (PMID 30760225, 2019). "We hypothesized that the PCT, CRP, WBC, and ESR might result in capabilities to diagnose sepsis and reflect prognosis." (PMID 31420921, 2019). "Moreover, such markers as white blood cells (WBC), neutrophils count, CRP, or procalcitonin showed to be insufficiently sensitive to discriminate SIRS and sepsis, especially when used alone." (PMID 30974881, 2019). "CRP but not WCC was also significantly higher in the sepsis group when compared to the ischaemia group." (PMID 31095593, 2019). "CRP, leucocytes, and PCT were partly available from post-surgery patients and healthy volunteers, while biomarkers were consistently available for patients with sepsis." (PMID 31396491, 2019). "The aim of this study was to evaluate whether Interleukin-6 (IL-6) could be a faster indicator of treatment success in adults with severe sepsis and septic shock compared to procalcitonin (PCT) and C-reactive protein (CRP)." (PMID 30760225, 2019).
Sepsis (continued). "The CRP and NLR values on the 1st and 3rd day of ICU stay in sepsis patients in the present study were assessed according to guidelines that suggested that the response to the initial antibiotic therapy should be assessed by a regression in biomarkers and clinical response within the first 48–72 h." (PMID 31648506, 2019). "In conclusion, our results suggest that IL-6 is better than PCT and CRP to predict the treatment success of non-surgical sepsis within the first 48–72 h." (PMID 30760225, 2019). "Sepsis resolved on day 14, with a negative blood culture and C-reactive protein (CRP) falling from 212 to 41; this improvement prompted cessation of antibiotic therapy." (PMID 30418554, 2019). "This is consistent with other studies, demonstrating that CRP did not allow early discrimination of nonsurvivors from survivors with postoperative sepsis." (PMID 31265174, 2019). "Therefore, in this study, we evaluated accessible biomarkers including PCT, CRP, ESR, and WBC in the clinical setting for their utility in the diagnosis and prognosis of revised sepsis." (PMID 31420921, 2019). "According to the literature, the most useful postmortem marker of sepsis-related deaths may be serum PCT, CRP, sTREM-1, and sIL-2R." (PMID 31661804, 2019). "Significant differences in NLCR values were observed between sepsis and non-sepsis patients (15.3 [10.8–38.2] (median [interquartile range] vs. 9.3 [6.2–14.5]; P<0.001), as well as for CRP level, PCT level and lymphocyte count." (PMID 30811475, 2019). "After empirical antibiotic therapy, the NLR and CRP were significantly higher on the 3rd day in the nonresponsive sepsis/septic shock patients." (PMID 31648506, 2019). "The primary purpose of this study was to determine the capability of NLR and plasma lactate to predict mortality during hospitalization and later (in 28 days) in patients with sepsis from the Department of Critical Care Medicine, compared to established sepsis‐related biomarkers (PCT and CRP)." (PMID 31265174, 2019). "Therefore, we pooled all samples from which leucocytes, CRP and PCT data were available and grouped them into “sepsis” (n = 148) and “controls” (n = 201)." (PMID 31396491, 2019). "Although we found significantly higher NLCR values in patients with sepsis compared to patients without sepsis, our results indicate that CRP and PCT level show more accuracy to detect sepsis." (PMID 30811475, 2019). "Besides, according to few studies in infants and neonates, together with CRP, NLR is an accurate sepsis predictor." (PMID 30974881, 2019). "In addition to CRP and PCT, interleukin-6 (IL-6) has been suggested as a biomarker in the context of critical illness and sepsis." (PMID 31569348, 2019). "Biomarkers of inflammation and sepsis investigated in foals and adult horses include lactate, soluble CD14 (sCD14), serum amyloid A, procalcitonin, C-reactive protein (CRP), haptoglobin (Hp), interleukin 1β (IL-1β), interleukin-10 (IL-10), and interleukin-6 (IL-6)." (PMID 30931316, 2019). "Thus, CRP being a late onset biomarker while, PCT being an early onset biomarker serve as substantial biomarkers for sepsis detection." (PMID 33117982, 2019). "The laboratory indicators used for the clinical diagnosis of sepsis include CRP, IL-6, IL-8, tumor necrosis factor-α (TNF-α) and PCT, none of which are ideal diagnostic indicators due to their deficiencies in diagnostic specificity and sensitivity." (PMID 29760745, 2018). "In line, kisspeptin levels did not correlate with established sepsis-markers routinely assessed in critically ill patients such as C-reactive protein (CRP), procalcitonin (PCT) and interleukin-6 (IL-6)." (PMID 30332461, 2018). "However, since the established biomarkers of sepsis, in particular PCT and CRP, are costly assayed, there is an opportunity for more affordable ones to gain clinical acceptance." (PMID 29861795, 2018). "This is most likely because CRP is usually viewed as a biomarker of inflammation rather than sepsis." (PMID 30332466, 2018).
Sepsis (continued). "In patients with sepsis, serum tenascin-C levels were significantly positively correlated with SOFA scores (P = 0.011), serum creatinine (P = 0.006), C-reactive protein (CRP) (P = 0.001), interleukin-6 (IL-6) (P < 0.001), and tumor necrosis factor α (TNF-α) (P = 0.026)." (PMID 30442110, 2018). "Nevertheless, at 24 h, CRP had a better sensitivity of 84% for late-onset sepsis and a high negative predictive value of 92%." (PMID 29382319, 2018). "Previously proposed markers for the differentiation of non-infectious SIRS and sepsis in adults like CRP, IL-6, and PCT performed only slightly better than chance and considerably worse than the model developed in the RF approach, when applied to our data." (PMID 29544449, 2018). "Both CRP and PCT can serve as significant indicators in evaluating therapeutic effects of sepsis." (PMID 30087610, 2018). "Concurrently, measured activity of the conventional inflammation biomarkers, CRP and WBCC, showed an initial increase in activity, peaking two days after the clinical onset of the sepsis." (PMID 29853783, 2018). "CSF protein levels were 0.89 g/l (SD 0.37) in neonates without fever or elevated CRP (n = 26) and not significantly different from neonates with possible sepsis (n = 218) with 0.92 g/l (SD 0.40)." (PMID 29540199, 2018). "We compared data from neonates with fever (temperature > 38.0 °C) and/or elevated C-reactive protein (CRP) levels (> 5 mg/l) (possible sepsis) with data from neonates without fever or CRP elevation." (PMID 29540199, 2018). "In multivariate lasso analyses, only CRP and HLA-DRA circulating RNA were repeatedly associated with sepsis, and no model performed better than CRP alone (ROC-AUC 0.76 [0.68–0.84])." (PMID 29404789, 2018). "A sepsis workup was performed on the day of admission, a report from blood culture and swab from a fissure showed no bacteria growth, and C-reactive protein (CRP) as well as complete blood count (CBC) were normal." (PMID 30595131, 2018). "In assessing the quality of the test, sensitivity, specificity, positive predictive value (PPV) and negative predictive value (NPV) of increased CRP for parasitemia, malaria and septicemia were calculated." (PMID 30080904, 2018). "Compared with the non-sepsis group, the sepsis group demonstrated significant increases in PCT but not in WBC or CRP." (PMID 29968788, 2018). "Meanwhile, in the sepsis group, the CD64 index was positively correlated with CRP." (PMID 29968788, 2018). "While there are studies on BP in sepsis, to our knowledge, there were no studies examining subjects in this intermediate group with mild to moderate CRP elevation." (PMID 29855349, 2018). "In addition, XBJ can shorten the mean length of hospitalization, the Acute Physiology and Chronic Health Evaluation-II score (APACHEII score), White Blood Cell (WBC), C-Reactive Protein (CRP), Neutrophil (NEU), and Temperature (T0) of patients with sepsis." (PMID 30344613, 2018). "At initial sepsis evaluation (T0), both CBC and CRP should be performed to increase sensitivity." (PMID 29382319, 2018). "Most likely, in children as well as in adults with diagnosed sepsis C-reactive protein levels are highly elevated without predicting final outcome." (PMID 30446841, 2018). "In the documented cases, including this case, the patients only developed high grade fever with high CRP and did not develop neutropenic sepsis." (PMID 30593283, 2018). "There were 116 (48%) false positive CRP tests at T24 (CRP > 10 and no late-onset sepsis): 14 were treated for necrotizing enterocolitis, 8 had tests taken when the infant was in a postoperative period and 38 had suspected ventilator-associated pneumonia." (PMID 29382319, 2018). "The routine sepsis screen like Total Leucocyte Count (TLC), Immature to Total neutrophil ratio (IT Ratio), Micro Erythrocyte Sedimentation Rate (Micro ESR), and C-reactive protein (CRP) is not specific indices of sepsis." (PMID 30154872, 2018).
Sepsis (continued). "A recent published meta-analysis indicated that compared with conventional therapies, XBJ as adjunctive therapy for sepsis could significantly decrease APACHE II score, 28-day mortality, temperature, and serum levels of PCT, WBC, CRP, and NEU." (PMID 30087610, 2018). "The major drawback of CRP is lack of specificity, and ultimately prognostication in sepsis is controversial; on the other hand, Procalcitonin has clearly showed mortality prediction value in meta-analysis." (PMID 29364941, 2018). "CRP level and MPV value were significantly higher in the sepsis group compared to non-sepsis group." (PMID 30190753, 2018). "Most of the routinely used investigations like TLC, IT Ratio, Micro ESR, and CRP are not specific indices of sepsis." (PMID 30154872, 2018). "The median CRP level was 47.8 mg/dl (10.2-119.5) in the sepsis group and 18.6 mg/dl (4.9-66.1) in the non-sepsis group." (PMID 30190753, 2018). "His C-reactive protein was 78 mg/l, erythrocyte sedimentation rate was 95 mm/first hour, and he was otherwise comfortable, showing no signs of sepsis beside the high grade fever." (PMID 30593283, 2018). "There was no significant reduction in the odds of dying during hospital stay in discharges with CRP and/or lactate use only when compared with discharges with no sepsis biomarker use." (PMID 30332466, 2018). "The C-reactive protein/albumin ratio (CAR), represented as a combination of serum CRP and ALB counts, was initially used as a new inflammation-based prognostic score for the purpose of predicting mortality in patients with sepsis." (PMID 29568406, 2018). "The sepsis group showed significantly higher WBC, PCT and CRP levels than the control group." (PMID 29968788, 2018). "Further comparisons indicated that the SOFA scores, APACHE II scores, PCT, Lac, and CRP were significantly higher in sepsis nonsurvivors than in survivors." (PMID 29463949, 2017). "The results of the present study suggest that hs-CRP is not inferior to PCT in the diagnosis of sepsis and septic shock in oldest old patients." (PMID 28764651, 2017). "Although the role of serum procalcitonin (PCT) and high-sensitivity C-reactive protein (hs-CRP) in the diagnosis of sepsis and septic shock is well studied, it has not been investigated among oldest old patients." (PMID 28764651, 2017). "While BNP levels can increase in some conditions such as renal failure or sepsis despite normal cardiac function, CRP is not directly influenced by cardiac function." (PMID 28841896, 2017). "In paediatrics, the most frequently employed biomarker to differentiate sepsis from non-infectious SIRS is the C-reactive protein (CRP), which, however, is highly non-specific and has an unfavourable kinetics." (PMID 28438138, 2017). "In particular, we questioned whether adding biomarkers to the clinical variables, such as SOFA score, high-sensitivity C-reactive protein (CRP), and WBC would improve the prediction of mortality in sepsis." (PMID 28271449, 2017). "Recently, some studies investigated candidate biomarkers to detect sepsis reported such as procalcitonin (PCT), C-reactive protein (CRP), lipopolysaccharide-binding protein (LBP), interleukins, provasopressin, and myeloid cells expressing triggering receptor-1 (TREM-1)." (PMID 28875483, 2017). "Under these conditions, DNI should be interpreted with caution, and other biomarkers, such as CRP and procalcitonin, might be included to assess the severity of SIRS or sepsis." (PMID 28320333, 2017). "There were two primary endpoints; one to determine the sensitivity and specificity of CRP against blood culture and second was to determine the negative predictive value of CRP in determining the duration of anti-biotic in neonates presenting with sepsis." (PMID 29492073, 2017).